SOCS6 (suppressor of cytokine signaling 6)
Diseases named in the same sentence as SOCS6 in open-access papers (continued):
Sharing a sentence is not in itself a finding about the gene and the disease.
Sepsis (1 paper, 2022). Sepsis is defined as life-threatening organ dysfunction caused by a dysregulated host response to infection. "Exosomes isolated from patients with sepsis lung injury were proven to cause lung bronchial epithelial cell injury through miR-1298-5p and its target SOCS6 via regulating STAT3 signaling pathway." (PMID 35898472, 2022).
T lymphoma (1 paper, 2017). "First, SOCS6 could inhibit antitumor immunity by suppressing effects of IFN-alpha, as described for SOCS3 in T lymphoma." (PMID 28924457, 2017).
tumor (22 papers, 2012 to 2025). "It was demonstrated that the expression level of SOCS6 was significantly associated with tumor size (P=0.001)." (PMID 34895274, 2021). "In the present study, it was revealed that SOCS6 expression in GIST was significantly associated with tumor size and was an independent prognostic factor for GIST patients." (PMID 34895274, 2021). "Consequently, tumor cells with loss of SOCS6 may have increased activation of insulin and KIT-signaling resulting in uncontrolled growth." (PMID 22363434, 2012). "PART1, also known as prostate androgen-regulated transcript 1, was identified in exosomes and affected tumor progression via the miR-17-5p/SOCS6 axis and miR-302a-3p/CDC25A axis." (PMID 38279317, 2024). "This miRNA targets and suppresses the suppressor of cytokine signaling 6 (SOCS6), which acts as a tumor suppressor, due to the inhibition of cytokine signaling pathways." (PMID 35892576, 2022). "Xenograft tumor mouse model showed that SOCS6 inhibited tumor growth and promoted radiosensitivity in vivo." (PMID 33712005, 2021). "To investigate the in vivo effect of SOCS6 overexpression on tumor growth, we performed xenograft experiments in an animal model." (PMID 33712005, 2021). "In our work, SOCS6 was significantly upregulated in tumor tissues, and was inversely correlated to miR-1260b." (PMID 30737371, 2019). "qPCR confirmed significantly lower SOCS6 copy number in the group with tumor recurrence in both training (p = 0.023) and test (p = 0.005) sets." (PMID 22363434, 2012). "Quantitation of the degree of SOCS6 methylation using mass spectrometry of amplification products with the Sequenom EpiTYPER assay was performed in 62 SCC tumor samples from the training set." (PMID 22363434, 2012). "We therefore evaluated the methylation status of SOCS6 in the training set of SCC tumor samples using two independent techniques: Illumina Infinium Methylation microarrays and MassARRAY® EpiTYPER analysis." (PMID 22363434, 2012). "Additionally, it was suggested that miR-21 influences the tumor microenvironment by modulating antioxidant enzymes like SOD2 and GPx1, as well as signaling suppressors SOCS1 and SOCS6, thereby promoting conditions favorable for tumor growth." (PMID 41465462, 2025). "Notably, DDP treatment significantly increased SOCS5 and SOCS6 expression in tumor tissues, and this phenomenon was further enhanced after the knockdown of miR-424-5p." (PMID 38439876, 2024). "SOCS6 overexpression significantly slowed tumor growth in vivo (P < 0.01)." (PMID 33712005, 2021). "For SOCS4 and SOCS6, only one study reporting increased expression in tumor tissues was identified." (PMID 34120621, 2021). "In our study, however, we revealed that SOCS6 was upregulated in BRCA tumor tissues, which may also be the case in different cancer types." (PMID 34120621, 2021). "Recent evidence suggests that SOCS6 can inactivate the JAK2/STAT3 pathway in tumor cells." (PMID 33937336, 2021). "According to Kaplan-Meier curve analysis, low SOCS6 expression (P=0.0059), tumor size>5 cm (P<0.001), necrosis of tumor (P<0.001), Mitotic index>5/50HPF(P=0.0001), moderate or high NIH risk grade (P<0.001) were significantly associated with worse OS of GIST patients." (PMID 34895274, 2021). "Our current study illustrated that SOCS6 played a tumor-suppressing role in ESCC." (PMID 33712005, 2021). "However, 14 and 22 of these studies showed statistically significant differences in SOCS5 and SOCS6 expression, respectively, between tumor and normal tissues." (PMID 34120621, 2021). "More recently, tumour suppressor activity was also identified in SOCS6." (PMID 24757565, 2014). "This suggests that even despite the presence of non-tumor cells, the detection of SOCS6 copy number alteration may have potential as a prognostic biomarker." (PMID 22363434, 2012). "However, SOCS6 expression was not significantly correlated with other variables including age, gender, tumor location, necrosis of tumor, mitotic index and NIH risk grade." (PMID 34895274, 2021).
tumor (continued). "Similarly, the SOCS6 gene, the top component of LV 624, is known to be directly involved in immune signaling via repression of cytokines and has also been found to be a selective tumor suppressor." (PMID 32098059, 2020). "In addition, we found decreased SOCS6 expression in the tumor tissues." (PMID 30737371, 2019). "SOCS1, SOCS6 and PTEN have been identified as tumor suppressors in a broad range of human malignancies, including NSCLC." (PMID 27811366, 2016). "Interestingly, the role of SOCS5, SOCS6, JAK2/STAT3, and PI3K/AKT pathways in DDP resistance of tumor cells has been well documented." (PMID 38439876, 2024). "The function of SOCS6, which has been shown to be a tumor suppressor in several cancers, has not been fully investigated up till now." (PMID 33712005, 2021). "Given that SOCS1, SOCS6, and PTEN are known to be critical tumor suppressors, we reasoned that restoring their expression by downregulating miRNA expression could be a good cancer treatment strategy." (PMID 27811366, 2016). "In addition, the elevated exosome miRNA-155 during the co-culture of tumor cells and adipocytes can promote the production and release of adipocytes CCL2 and CCL5 by targeting the SOCS6/STAT3 pathway, thereby regulating the function and polarity of macrophages and promoting tumor progression." (PMID 37666813, 2023). "According to Kaplan-Meier curve analysis, low SOCS6 expression (P=0.0071), non-stomach GIST (P=0.0107), tumor size>5 cm (P<0.001), necrosis of tumor (P<0.001), Mitotic index>5/50HPF(P<0.001), moderate or high NIH risk grade (P<0.001) were significantly associated with worse RFS of GIST patients." (PMID 34895274, 2021).
cancer (20 papers, 2014 to 2026). A tumor composed of atypical neoplastic, often pleomorphic cells that invade other tissues. "SOCS1 induces apoptosis and inhibits the growth of cancer cells, whereas SOCS6 is associated with disease recurrence." (PMID 33294082, 2020). "Additionally, SOCS6 regulates cancer cell susceptibility to radiation and chemotherapy, potentially suppressing tumour growth in various cancers through epigenetic and non-coding RNA processes." (PMID 41514679, 2026). "Lower SOCS6 levels are associated with poor prognosis in several cancer types." (PMID 41514679, 2026). "The locus (18q22.2) where human SOCS6 resides is commonly associated with malignant tumors." (PMID 34895274, 2021). "SOCS6 inhibits tumour growth in a variety of cancers, including glioblastoma, bladder carcinoma, non-small cell lung, prostate, lung, oesophageal squamous cell carcinoma, cervical, and gastric cancer." (PMID 41514679, 2026). "When SOCS6 expression is downregulated or deleted in experimental designs, it impacts on cancer progression via epigenetic pathways like changes in DNA methylation." (PMID 41514679, 2026). "There are various small non-coding RNAs (miRNAs, lncRNAs, and circRNAs) that regulate SOCS6 expression; this, in turn, affects cancer progression and the efficacy of therapeutic interventions." (PMID 41514679, 2026). "have demonstrated that the Suppressor of Cytokine Signaling 1 (SOCS1), Suppressor of Cytokine Signaling 6 (SOCS6), and Phosphatase and Tensin Homolog (PTEN) are implicated in various human malignant tumors, including NSCLC." (PMID 39963112, 2025). "Many studies reporting that down-regulation of SOCS6 plays vital roles in promoting progression of malignant tumors have been published." (PMID 34895274, 2021). "For SOCS5 and SOCS6, 413 and 412 studies of multiple cancer types were taken into consideration, respectively." (PMID 34120621, 2021). "In HPV+ Eca109 cells, cell spheres formed in SOCS6 overexpression group was significantly reduced compared with the control group, which means cancer cell stemness was attenuated (P < 0.01)." (PMID 33712005, 2021). "Immunoblotting showed that SOCS6 protein levels were low in a variety of colorectal, breast, and other cancer cell lines, compared to primary human BJ cells (Fig5E)." (PMID 25180228, 2014). "We note that the magnitude of the effect of SOCS6 depletion was less in the cancer cell lines than in BJ cells, perhaps reflecting the lower starting level of SOCS6 protein in these cells." (PMID 25180228, 2014). "SOCS6 is downregulated in a variety of cancers and has capacity to inhibit tumorigenesis when expressed in cell lines derived from gastric cancer (AGS and AZ-521) as well as nonsmall cell lung cancer (H1299) and kidney (HEK293)." (PMID 24757565, 2014). "Given the evidence that RasV12 downregulates SOCS6 and that SOCS6 depletion is required for efficient RasV12-mediated cellular transformation, we sought to explore the cancer relevance of SOCS6." (PMID 25180228, 2014). "Numerous researches have indicated that SOCS5 and SOCS6 act as cancer suppressors in NSCL." (PMID 38439876, 2024). "Taken together, these results indicate that SOCS6 is a negative regulator of ESCC cancer cell stemness, a role that may account for the increases in radiosensitivity of ESCC cells overexpressing SOCS6." (PMID 33712005, 2021). "Furthermore, SOCS6 had been reported to regulate sensitivity of cancer cells to radiotherapy and chemotherapy." (PMID 34895274, 2021). "Since cancer cell stemness is considered an essential factor of radioresistance, we further investigated whether SOCS6 expression affects the stemness of ESCC cells." (PMID 33712005, 2021). "By far SOCS6 has been reported to be deleted in many malignant tumors." (PMID 34895274, 2021).
cancer (continued). "Loss of tight regulation of the stromal cell factor (SCF) receptor, C-KIT, can lead to the development of several human cancers, and SOCS6 can bind directly to the juxtamembrane (JM) region of C-KIT following SCF stimulation and phosphorylation of murine C-KIT Y567 (human Y568)." (PMID 24757565, 2014). "The silencing of SOCS6 disables this inhibitory regulation, resulting in augmented proliferation and viability, in accordance with prior research indicating that the absence of SOCS6 is associated with heightened cancer cell growth." (PMID 41514679, 2026). "The suppressor of cytokine signaling proteins family, of which SOCS6 is a member, is involved in a classical negative feedback circuit for cytokine signaling and has been implicated in development of various diseases, including cancer." (PMID 33937336, 2021). "The findings reveal that reducing SOCS6 increases cancer cell survival and migration, while changes in EPOR expression influence SOCS6 levels and cell survival differently depending on the cell type." (PMID 41514679, 2026). "Many investigations have shown that SOCS6 suppresses pathways like PI3K/Akt and MAPK/ERK, which are often elevated in colorectal cancer and other cancers to promote cell growth and survival." (PMID 41514679, 2026). "The results indicated that the promoter methylation levels of SOCS1 (p– = 7.379E‐07), SOCS3 (p = 4.534E‐10), SOCS5 (p = 1E‐12), SOCS6 (p = 5.534E‐11), and CISH (2.273E‐05) were lower in cancer tissues than in normal tissues." (PMID 39307915, 2024). "miR-494-3p enhances core hallmarks of cancer by targeting several important tumor suppressor genes, such as PTEN, SOCS6 and BMI1." (PMID 35073936, 2022). "The findings are in line with the current thinking that complex networks of signal transduction and micro-environmental factors influence cancer metastasis and invasion, with SOCS6 having a role but not the only one." (PMID 41514679, 2026). "Exercise-based approaches have recently been shown to impact the rno-miRNA-regulated target cancer gene candidates ITPR3, SOCS6, ITGA6, and NKX2-1 as biomarkers for cancer prognosis in rheumatoid arthritis diagnoses in pristane-induced arthritis (PIA) rat models." (PMID 36012617, 2022). "In the context of YAP/TAZ upregulation induced by E6 in cancer, it has been previously suggested that E6 could induce YAP through the downregulation of SOCS6, a known negative regulator of YAP." (PMID 34439242, 2021). "The inverse correlation between SOCS6 and AREG mRNA levels in human cancers was intriguing." (PMID 25180228, 2014). "SOCS6 levels are low in several cancers, where they show a negative correlation with the levels of the YAP target Amphiregulin." (PMID 25180228, 2014).
infection (4 papers, 2016 to 2022). The state of being infected such as from the introduction of a foreign agent such as serum, vaccine, antigenic substance or organism. "The expression of the SOCS-2 and SOCS-6 genes increased in B. mori after infection by viral, bacterial, and fungal pathogens." (PMID 36142300, 2022). "Using this approach, we observed that mixed-infection of MDMs induces a synergistic production of IP-10 which can be related to a miRNA-200a/JAK-STAT/SOCS-6 regulatory pathway." (PMID 27922126, 2016). "However, dietary BLJ supplementation remarkably downregulated TLR-4 and TRAF-6 gene expression levels, decreased IL-1β gene expression levels and increased A20 and SOCS-6 mRNA levels in the jejunal mucosa of broilers regardless of NE infection." (PMID 32110391, 2020).
cardiac diseases (1 paper, 2022). "Finally, we review the literature associated with the QK/miR-19b/Socs6 axis and discuss whether it may have potential in the improved management of cardiac diseases." (PMID 35126805, 2022). "The QK/miR-19b/Socs6 axis plays a vital role in regulation of mitochondrial fission and cardiomyocyte apoptosis and could form the basis of future research in the development of therapies for the management of cardiac diseases." (PMID 35126805, 2022).
SOCS6 also shares sentences with these, for which no sentence is quoted: lung carcinoma (4 papers); asthma (2); esophageal squamous cell carcinoma (2); Zinc deficiency (2); Autoimmunity (1); chlamydia (1); endometrial cancer (1); gastrointestinal stromal tumor (1); head and neck cancer (1); head and neck squamous cell carcinoma (1); immune disease (1); leukemia (1); lung adenocarcinoma (1); Lung Squamous Cell Carcinoma (1); lymph node metastasis (1); myelofibrosis (1); myeloid malignancies (1); myocardial infarction (1); neurological diseases (1); pancreatic adenocarcinoma (1); prostate tumor (1); rectal adenocarcinomas (1); small cell lung carcinoma (1).